PTN (pleiotrophin)
Diseases named in the same sentence as PTN in open-access papers (continued):
Sharing a sentence is not in itself a finding about the gene and the disease.
tumor (continued). "To address whether the pro-tumorigenic effect of TAMs is exerted through PTPRZ1 expressed on GSCs, we determined the effect of PTN-expressing MLCs on the growth of PTPRZ1+ and PTPRZ1− tumours." (PMID 28569747, 2017). "To confirm that the antitumour effect of anti-PTPRZ1 antibody is exerted through blocking PTN–PTPRZ1 axis between GSC and TAMs, we constructed GBM xenografts co-implanted with GSCs (T4121) and MLCs, and administrated the tumour-bearing mice with anti-PTPRZ1 antibody." (PMID 28569747, 2017). "PTN is not an oncogene on its own, but potentiates tumor initiation induced by e.g. PDGFB by augmenting Akt activation, leading to enhanced proliferation of neural progenitor cells." (PMID 27806344, 2016). "Although the role of PTN has been studied in several in vivo models of tumour growth, there are no in vivo studies on the role of endogenous PTN in physiological angiogenesis." (PMID 22423616, 2012). "Although implication of endogenous PTN has been studied in several in vivo models of tumour angiogenesis, its role in physiological angiogenesis has not been addressed." (PMID 22423616, 2012). "Likewise, the growth factor pleiotrophin (PTN/HB-GAM/HARP) is overexpressed in glioblastoma and is rate limiting for tumor growth, thus representing an attractive target gene for therapeutic knockdown approaches." (PMID 27721338, 2011). "From previous studies, it is known that either but not both the N- or C-terminal domains is required for pleiotrophin activity, and that the C-terminal domain is involved in the mitogenic, angiogenic, and tumor formation activities of this growth factor." (PMID 20738847, 2010). "Heparin-binding growth factor (PTN)-secreting tubulointerstitial-like progenitor cells are more enriched in IBC patients and can mediate the proliferation of immature perivascular cells via the NRP1 receptor, thereby promoting the invasion and metastasis of IBC tumour cells." (PMID 40624675, 2025). "We then performed quantitative real-time PCR (qRT-PCR) analysis for four cell surface receptor genes (PTN, CD24, BMP7, and CADM1), because their protein products are easily detectable by molecular diagnosis and are also related to cell survival, proliferation, or tumor growth." (PMID 33298865, 2020). "Moreover, we found that the pleiotrophin (PTN) signaling pathway was also highly expressed around these regions, suggesting that SNV group 2 may be responsible for the TAM microenvironment at the tumor margins." (PMID 40515555, 2025). "All pRMS tumor clusters use the MIF-CD74 pathway to suppress the immune response, while APP, PTN, and CXCL12 signaling are employed predominantly by the non-myogenic tumor clusters." (PMID 41373578, 2025). "Ligand-receptor (L-R) pair analyses indicated that tumor cells with high REN expression engaged NK and T cells through specific ligand-receptor pairs—namely PTN-NCL and COL4A1-CD44, interactions that were largely absent in low-REN-expressing tumor cells." (PMID 40534868, 2025). "In contrast, PTN expression and the infiltration of CD163+ M2 TAMs were markedly reduced in tumour areas lacking GSCs, suggesting a co-distribution among GSCs, M2 TAMs and PTN." (PMID 28569747, 2017). "In contrast, PTN+ cells did not exhibited significant spatial patterns, suggesting that, in addition to CD44+ tumor cells, other cells may contribute to PTN signaling activation and regulation in a manner independent of tumor edge CAFs and neutrophils." (PMID 40069574, 2025). "Moreover, many genes (PTN, SIAH2, FAM111B, TMEM43, FOSL2, TRIB1 and SPATA1) were hypomethylated regardless of tumor grade." (PMID 36850002, 2023).
cancer (88 papers, 2002 to 2026). A tumor composed of atypical neoplastic, often pleomorphic cells that invade other tissues. "In vitro experiments and immunofluorescence staining of clinical samples validated pleiotrophin (PTN) signaling in promoting cancer-associated fibroblasts (CAFs) phenotypic transition and CRC progression." (PMID 40069574, 2025). "In summary, our study identifies PTN as a metastasis-associated factor that can facilitate local immune suppression favoring cancer cell colonization at secondary sites and therefore presents a novel therapeutic target in the treatment of metastatic TNBC." (PMID 36828390, 2023). "In humans, the expression of PTN is increased in several types of cancer, and overexpression is usually associated with a poor prognosis." (PMID 37691636, 2023). "Abnormal levels of PTN have been associated with a number of diseases, including many types of cancer and inflammatory diseases." (PMID 35053198, 2021). "PTN is a growth factor that regulates several cellular functions, and its high expression is associated with many cancer types." (PMID 33435254, 2021). "Pleiotrophin (PTN), a neurotrophic growth factor, has been linked to the malignant characteristics of various cancer types." (PMID 28969035, 2017). "Pleiotrophin is a protein associated with cancer progression, and luteolin’s ability to modulate its expression through miRNA could be a promising approach for cancer therapy." (PMID 39061884, 2024). "Thus far, our data indicate that PTN-stimulated NF-κB activation causes cytokine expression especially CXCL5 in cancer cells, which leads to neutrophil recruitment." (PMID 36828390, 2023). "Furthermore, retrospective studies based on clinical specimens have demonstrated the potential of PTN as a diagnostic and prognostic biomarker for cancer patients." (PMID 28969035, 2017). "Thus, we further investigated whether HBV infection affected the mediatory role of PTN on cancer-associated fibroblast-related HCC." (PMID 37259127, 2023). "This MALL-SDC4 program promotes RhoA/phosphorylated myosin light chain 2 (p-MLC2)-dependent amoeboid motility and sensitizes cancer cells to Schwann cell-derived pleiotrophin, strengthening directed neural invasion." (PMID 42017444, 2026). "Functional assays in endothelial cells from PTN knockout mice or endothelial and cancer cells following the downregulation of PTN expression showed that PTN negatively affects chemical hypoxia-induced cell proliferation and migration." (PMID 40361445, 2025). "The results demonstrated that cancer cells interact with stromal cells via the PTN-NCL and MIF-(CD74+CXCR4) signaling pathways." (PMID 40642071, 2025). "Pleiotrophin (PTN) is a secreted protein that activates cell migration in endothelial and cancer cells that express ανβ3 integrin but has inhibitory effects in cells that do not express ανβ3 integrin." (PMID 40361445, 2025). "PTN can influence endothelial and cancer cell functions through numerous cell surface receptors, including PTPRZ." (PMID 38999976, 2024). "Pleiotrophin (PTN) produced by TAMs is responsible for, among other effects, promoting cell proliferation, migration, and the induction of angiogenesis, and it contributes to increasing the percentage of cancer stem cells through the PTN/β-catenin pathway." (PMID 38473285, 2024). "The first identified soluble ligand of PTPRZ was pleiotrophin (PTN), a secreted heparin-binding growth factor highly expressed in the embryonic nervous system and other embryonic organs, and overexpressed in several cancer cell lines." (PMID 38999976, 2024). "Among the secretory factors downregulated in CAF-200 cells, VEGF-D and PTN demonstrated the ability to enhance cancer cell migration and invasion." (PMID 38766528, 2024). "NRP2-VEGFR signaling facilitates the secretion of VEGF-D and pleiotrophin from CAFs, leading to the activation of cancer cell migration and invasion." (PMID 38766528, 2024).
cancer (continued). "Fibroblast growth factor and signaling proteins are known to increase PTN expression level, resulting in activation of fibroblasts which then aggressively promote cancer progression." (PMID 37259127, 2023). "We propose that this is mediated in part by the inhibition of PTN-mediated activation of NF-κB pathway in cancer cells." (PMID 36828390, 2023). "Cancer cells isolated from metastatic lungs had higher PTN expression compared with cancer cells isolated from primary tumors." (PMID 36828390, 2023). "scRNAseq data from late-stage mouse MMTV-PyMT tumors also show that PTN is produced by endothelial cells and a subpopulation of cancer cells." (PMID 36828390, 2023). "PTN is a heparin-binding growth factor, with potent mitogenic and angiogenic activity, and a crucial regulator of cancer metastasis, bone development, and bone repair." (PMID 37082621, 2023). "A possibility is that PTN expression is induced as part of an essential adaptation process triggered in cancer cells when they colonize a new site." (PMID 36828390, 2023). "As a small cationic protein, PTN is involved in a variety of biological processes including cancer cell growth and metastasis." (PMID 38250070, 2023). "Mechanistically, we found PTN activates the NF-κB pathway in cancer cells, resulting in elevated expression of cytokines including CXCL5." (PMID 36828390, 2023). "To determine if PTN is relevant in cancer cell seeding and colonization of secondary sites, we injected E0771-LG cells via the tail vein." (PMID 36828390, 2023). "PTN in the metastatic microenvironment activates the NF-κB pathway in cancer cells, leading to increased cytokine production including CXCL5, which results in elevated neutrophil recruitment and contributes to immune suppression." (PMID 36828390, 2023). "Many of these genes, such as VIM, FOSL2, PTN, GPR3, SIAH2, UPP1, S100A2 are associated with cell migration and epithelial-mesenchymal transition (EMT) in several cancers." (PMID 36850002, 2023). "Mechanistically, we find that PTN activates NF-κB in cancer cells leading to altered cytokine production, subsequent neutrophil recruitment, and an immune suppressive microenvironment." (PMID 36828390, 2023). "We validated the scRNAseq data in patient and mouse MMTV-PyMT tumors by multiplex staining of PTN (by IHC or RNA-FISH) with cancer cell (panCK or PyMT) and endothelial cell (CD31) markers." (PMID 36828390, 2023). "According to the results of a meta-analysis, increased expression of PTN was substantially associated with advanced TNM stage and dismal OS in cancer patients." (PMID 35281077, 2022). "It turned out that a cluster of cancer cells featured by high expression of PTN scored highest among the 7 clusters identified." (PMID 36036011, 2022). "PTN, which plays a complex role in angiogenesis in multiple diseases, including cancer, likely plays a pro-angiogenic role in diabetic retinopathy." (PMID 35882889, 2022). "This agrees with actions in other tissues such as an ability of PTN to increase the number of hematopoietic stem cells, microglia and the growth of hepatic and multiple other cancers." (PMID 35250852, 2022). "For example, it is proposed that PTN promotes cancer progression through increased vascular endothelial growth factor deposition at the vasculature leading to vascular disruption." (PMID 35365620, 2022). "Specifically, M1 and M2 macrophages targeted other cells in the GALECTIN, GRN and SPP1 signaling pathway networks, and GBM cancer cells regulated other cells in the MK and PTN signaling pathway network." (PMID 35558067, 2022). "PTN is also a prognostic factor in cancer that has been proven to be negatively correlated to overall survival." (PMID 35047379, 2021). "PTN levels were again elevated in the metastatic when compared to the cancer-free, CPG1 and CPG5 patient groups consistent with the findings in the proteomic assay." (PMID 33288843, 2021).
cancer (continued). "PTN binds to different receptors that mediate actions in different organs and pathological conditions, particularly cancer." (PMID 34206170, 2021). "PTN, overexpressed in numerous cancers, is involved in cell transformation, growth, survival, migration and angiogenesis." (PMID 34663387, 2021). "During the past few years, increasing evidences suggested an essential role of MK and PTN in carcinomas and acute and chronic inflammatory diseases." (PMID 32153561, 2020). "It has been shown that overexpression of PTN has multiple effects on various cancers through diverse mechanisms." (PMID 30427932, 2018). "The ALK/GSK3β/β-catenin pathway is an impor-tant PTN-induced pathway that is involved in neural development and cancer progression." (PMID 28969035, 2017). "Our study indicated that the PTN–PTPRZ1 signalling also plays an essential role in the maintenance of cancer stem cells in GBMs." (PMID 28569747, 2017). "The high expression levels of midkine and pleiotrophin in many types of cancers make them excellent as biomarkers and therapeutic targets for cancer." (PMID 27903979, 2017). "The expression of PTN in the adult is limited to the hippocampus in an activity-dependent manner, making it a very attractive target for cancer therapy." (PMID 28562667, 2017). "In bone metastases, OBs and newly embedded osteocytes are PTN-positive, but only in areas of cancer cell infiltration." (PMID 25485970, 2014). "An increase in PTN expression has been observed in the uterus during gestation, in the human placenta and during bone repair, inflammatory diseases and in human cancers." (PMID 23077670, 2012). "In a complementary, unbiased screen, mass spectrometry analysis of cancer cell supernatants identified PTN as the major ligand for the ALK ECD that had been immobilized on SELDI mass spectrometry chips." (PMID 23267434, 2012). "By performing subcellular fractionation assay, similar pattern of co-localization of PTN with NCL was also observed in U87MG cancer cells, suggesting that the interaction between PTN and NCL is common to several types of cells." (PMID 22423616, 2012). "In NIH3T3 fibroblasts, PTN leads to transformation, whereas overexpression of a dominant negative, mutant PTN protein reverses the transformed phenotype of breast and other cancer cell lines." (PMID 23077670, 2012). "PTN is a heparin‐binding growth factor and has been reported to play an important role in cell–cell adhesion, cell motility, cell division, immune cell migration, and angiogenesis in various cancers." (PMID 40776410, 2025). "Alternatively, PTN-expressing cancer cells may be better equipped to survive the insults of the metastatic cascade." (PMID 36828390, 2023). "In particular, PTN had the most significant association with B cells memory and T cells CD8, which further confirmed PTN’s role in mediation of B cells and CD8 + T cells in the cancer-associated fibroblast-related HCC." (PMID 37259127, 2023). "We also found that the interaction of PTN- SDC1 and PTN- NCL may mediate the effect of B cells and CD8 + T cells on cancer-associated fibroblast-related HCC." (PMID 37259127, 2023). "By incorporating spatial transcriptomic data, we found a cluster of cells featured by high expression of PTN exhibited the highest m7G score and may communicate with adjacent cancer cells via SPP1 and PTN signaling pathways." (PMID 36036011, 2022). "PTN is highly expressed in embryonic and postnatal development, while it is quite down-regulated in adult life; however, it is strongly expressed in lung tumor and other types of cancer." (PMID 34262872, 2021). "Although study has unveiled the genetic association of MK and PTN in human cancer, the association between common single-nucleotide polymorphisms (SNPs) in the MK and PTN genes and SLE susceptibility has not yet been elucidated." (PMID 32153561, 2020).
cancer (continued). "Based on previous results, overexpression PTN could be detected in a wide variety of human cancers, and is believed to be proto‐oncogenic." (PMID 30635982, 2019). "PTN was found to be up-regulated in various types of human cancers, and overexpression of PTN was suggested to promote cell proliferation and angiogenesis, contributing to cancer progression." (PMID 29299168, 2017). "Pleiotrophin (PTN) is a heparin-binding growth factor which is overexpressed in many cancers." (PMID 26914549, 2016). "RPTPβ/ζ and PTN are expressed in endothelial cells and over-expressed in several types of cancer." (PMID 25644401, 2015). "PTN is highly expressed in the nervous system in addition to its high expression in some cancers." (PMID 23267434, 2012). "Disease outcomes relative to gene expression of ALK, LTK, PTN, and MK in clinical cancer specimen." (PMID 23267434, 2012). "Although pleiotrophin has been shown to promote neurite outgrowth in the developing brain, elevated concentrations of this growth factor are found in many types of tumors as well as in the plasma of patients with different types of cancer." (PMID 20738847, 2010). "Therefore, the PTN-SDC1 and PTN-NCL interactions may regulate cancer-associated fibroblast in HCC by modulating B cells and CD8 + T cells, and PTN may be a novel mediator of CAF in HCC." (PMID 37259127, 2023). "Thus, PTN might provide a promising cancer liquid biopsy marker, which warrants further research to evaluate the utility of PTN as a clinical test in different types of cancer." (PMID 37691636, 2023). "Interestingly, our data suggested that cells with the highest m7G score also exhibited a high expression level of microglia/macrophage markers CD63, and these cells were predicted to communicate with a cluster of cells with high expression of cancer stem cell maker THY1 via PTN pathway." (PMID 36036011, 2022). "In addition to cancer regions, sample 2 could also distinguish regions of breast ductal epithelial cells (cluster 6) with high expression levels of PTN, RGS2, CLU, and KRT15." (PMID 34799559, 2021). "Thus PTN becomes an attractive target for cancer gene therapy." (PMID 28562667, 2017). "NCL is over-expressed on the plasma membrane of cancer and activated endothelial cells and has been shown to play critical roles in the modulation of tumorigenesis and angiogenesis through its interaction with a variety of ligands, among which tumor homing peptide F3, endostatin, P-selectin and PTN." (PMID 25644401, 2015). "In conclusion, hypoxia or chemical hypoxia regulates PTN and PTPRZ1 expression to restrict its stimulatory effects on endothelial and cancer cells." (PMID 40361445, 2025). "We found that cancer epithelial cells with elevated SHCBP1 expression exhibited a strong interaction with stromal cells through the EGF, VEGF, IGFBP, CypA, GRN, and PTN signaling pathways." (PMID 40799237, 2025). "Although our study identified the roles of PTN and VEGF-D in the interplay between CAFs and cancer cells, further investigation is warranted to explore the crosstalk between NRP2 and these proteins." (PMID 38766528, 2024). "By combining FISH and multiplex IHC, we stained metastatic lesions in MMTV-PyMT lungs for PTN (RNA-FISH), PyMT antigen (cancer cell marker), CD31 (endothelial marker), CD45 (pan-immune cell marker), and podoplanin (fibroblast, lymphatic maker)." (PMID 36828390, 2023). "Thus, PTN may be a promising therapeutic target for cancer treatment." (PMID 37259127, 2023). "While cancer cells are the major source of PTN in the TME, we found that multiple stromal cells including endothelial cells also contribute to PTN expression." (PMID 36828390, 2023). "Since PTN can be produced by cancer cells and stromal components, we generated Ptn-nullMMTV-PyMT FVB mice to study the function of PTN in breast tumor progression." (PMID 36828390, 2023).